RPS21 (ribosomal protein S21)
Description:
Component of the small ribosomal subunit. The ribosome is a large ribonucleoprotein complex responsible for the synthesis of proteins in the cell.
Synonyms: S21; eS21; HLDF
Tractability: Small molecule: an approved drug acts on it; a structure with a bound ligand is known; a high-quality ligand is known. PROTAC: UniProt records ubiquitination sites on it; ubiquitination databases record sites on it; its protein half-life has been measured; a small molecule that binds it is known. Other modalities: a drug acting on it is in phase 2 or 3 trials.
Target class: Other cytosolic protein
Gene: Protein-coding gene on chromosome 20 (62,385,948 to 62,388,534, forward strand). Ensembl gene ENSG00000171858.
Subcellular location: Cytoplasm, cytosol; Cytoplasm; Rough endoplasmic reticulum
Subcellular location (Human Protein Atlas): Cytosol; Endoplasmic reticulum
Pathways (Reactome):
Metabolism of proteins: Eukaryotic Translation Termination; Formation of a pool of free 40S subunits; Formation of the ternary complex, and subsequently, the 43S complex; GTP hydrolysis and joining of the 60S ribosomal subunit; L13a-mediated translational silencing of Ceruloplasmin expression; PELO:HBS1L and ABCE1 dissociate a ribosome on a non-stop mRNA; Peptide chain elongation; Ribosomal scanning and start codon recognition; SRP-dependent cotranslational protein targeting to membrane; Translation initiation complex formation; ZNF598 and the Ribosome-associated Quality Trigger (RQT) complex dissociate a ribosome stalled on a no-go mRNA
Disease: SARS-CoV-1 modulates host translation machinery; SARS-CoV-2 modulates host translation machinery; Viral mRNA Translation
Metabolism of RNA: Major pathway of rRNA processing in the nucleolus and cytosol; Nonsense Mediated Decay (NMD) enhanced by the Exon Junction Complex (EJC); Nonsense Mediated Decay (NMD) independent of the Exon Junction Complex (EJC)
Cellular responses to stimuli: Response of EIF2AK4 (GCN2) to amino acid deficiency
Developmental Biology: Regulation of expression of SLITs and ROBOs
Metabolism: Selenocysteine synthesis
Gene Ontology:
Molecular function: protein binding; RNA binding; structural constituent of ribosome
Biological process: cytoplasmic translation; endonucleolytic cleavage in ITS1 to separate SSU-rRNA from 5.8S rRNA and LSU-rRNA from tricistronic rRNA transcript (SSU-rRNA, 5.8S rRNA, LSU-rRNA); endonucleolytic cleavage to generate mature 3'-end of SSU-rRNA from (SSU-rRNA, 5.8S rRNA, LSU-rRNA); translation
Cellular component: cytosol; cytosolic ribosome; cytosolic small ribosomal subunit; small ribosomal subunit; cytoplasm; nucleoplasm; rough endoplasmic reticulum; ribosome; synapse
Genetic constraint (gnomAD): Loss-of-function variants: 6 observed, 13.17 expected, observed/expected ratio (o/e) 0.46, 90% interval 0.25 to 0.9. The synonymous counts are far from expectation, so gnomAD's model fits this gene poorly and the ratio says little. Missense variants: 85 observed, 117.8 expected, observed/expected ratio (o/e) 0.72, 90% interval 0.61 to 0.86. Synonymous variants: 61 observed, 44.08 expected, observed/expected ratio (o/e) 1.38, 90% interval 1.12 to 1.71.
Homologues: Orthologues: dog RPS21 (100% identical), guinea pig RPS21 (100% identical), macaque RPS21 (100% identical), pig RPS21 (100% identical), mouse Rps21 (95% identical), rat Rps21 (95% identical), rat Rps21-ps1 (94% identical), tropical clawed frog rps21 (93% identical), rat LOC100359505 (90% identical), zebrafish rps21 (88% identical), Drosophila melanogaster RpS21 (73% identical), rabbit RPS21 (72% identical), and 1 more.
Diseases named in the same sentence as RPS21 in open-access papers:
RPS21 is named in the same sentence as 26 diseases in open-access papers, as found by Europe PMC text mining. Sharing a sentence is not in itself a finding about the gene and the disease. The quoted sentences say what the papers report.
prostate carcinoma (8 papers, 2017 to 2024). A carcinoma that arises from epithelial cells of the prostate gland. "Two somatic mutations (c.62A>G and c.200_217del18) of the rps21 gene have also been previously identified in a selection of prostate carcinoma samples from the COSMIC database (Cosmic database, accessed September 2016)." (PMID 29016636, 2017). "Furthermore, a significant upregulation of RPL22L1 and RPS21 expression in prostate cancer tissues was observed, suggesting their potential utility as diagnostic markers for prostate cancer." (PMID 39684863, 2024). "For example, RPS19, RPS21, and RPS24 can be used as biomarkers for prostate cancer, and ribosome dysfunction is associated with the pathogenesis of nasopharyngeal carcinoma and can promote breast cancer metastasis." (PMID 34796111, 2021). "Among our ribosome genes, over-expressed RPS21 promoted prostate cancer (PCa) cell proliferation, migration, and invasion, inhibited PCa cell apoptosis, and was suggested as a promising biomarker, with a potential application in diagnosis or treatment." (PMID 34760386, 2021). "Recently, Rps21 was described as a human oncogene, especially in prostate cancer and osteosarcoma." (PMID 33949947, 2021). "The top 10 genes upregulated in TRAMP mice are TNFSF, RPL22, EIF4, SLC2A, LMO2/3, KRT, RPS21, RPS19, RPL21, and NEK of which all 10 were upregulated in human prostate cancer dataset." (PMID 30972102, 2019). "Our results show that RPS19, RPS21 or RPS24 are upregulated in malignant tissue and may serve as putative biomarkers for prostate cancer." (PMID 29016636, 2017). "Ribosomal protein s21 (RPS21) is a ribosome-related protein, which has been shown to play an important role in ribosomal biogenesis and may affect the occurrence and development of osteosarcoma and prostate cancer through the RAS/MAPK pathway." (PMID 34194482, 2021).
colorectal cancer (4 papers, 2020 to 2024). A primary or metastatic malignant neoplasm that affects the colon or rectum. "The trans-targets RPS21 and ZNF773 are also associated with colorectal cancer." (PMID 33957961, 2021).
osteosarcoma (4 papers, 2020 to 2022). A usually aggressive malignant bone-forming mesenchymal neoplasm, predominantly affecting adolescents and young adults. "In contrast, fewer studies have examined RPS21, and a recent study found that RPS21 plays an essential role in the invasive behaviour of osteosarcoma cells through the inactivation of the mitogen-activated protein kinase (MAPK) pathway." (PMID 36569748, 2022). "While this manuscript was in review, a recent study revealed that downregulation of human RPS21 inhibits metastatic behavior of osteosarcoma cells in a MAPK-dependent manner, underscoring the potential human relevance of our findings here." (PMID 33296356, 2020).
breast carcinoma (3 papers, 2020 to 2021). "Collectively, signaling protein analysis revealed a highly activated pathway of post-translational modification and protein transport to the rough endoplasmic reticulum (via GFM, MRPS12, RPS21, and SRP9), suggested circuitry to predict breast cancer outcomes." (PMID 32252260, 2020).
viral infection (2 papers, 2021 to 2025). "The median expression of some genes (CTBP1, LAPTM4B, CFAP45, DSC2, LAMP1, EXOG, RPS21, and SIRPB1) was higher in bacterial compared to viral infection." (PMID 41496780, 2025). "Although increasing numbers of RPs are involved in viral infections of plants, the role of RPS21 during viral infection, if any, has not been characterized yet." (PMID 33995313, 2021).
colon cancer (1 paper, 2024). "While evidence of HSPH1 associating with colon cancer abounds, current research on RPS21 in colon cancer, regarding its expression levels, functions, and potential therapeutic targets, is not yet comprehensive." (PMID 39872660, 2024). "In colon tissue, we noted regulatory effects of estrogen on colon cancer-related risk genes such as RPS21 and HSPH1." (PMID 39872660, 2024).
energy metabolism disorder (1 paper, 2026). "RPS21 may regulate PPARGC1A expression by interacting with hsa-mir-193b-3p, thereby influencing mitochondrial biogenesis and autophagy, contributing to energy metabolism disorder in retinal cells and playing a role in DR progression." (PMID 41601931, 2026).
glioblastoma (1 paper, 2019). The most malignant astrocytic tumor (WHO grade IV). "AP1B1, adaptor related protein complex 1 beta 1 subunit; CAPZA2, F-actin-capping protein subunit alpha-2; CCT5, chaperonin containing TCP1 subunit 5; GBAS, glioblastoma amplified sequence; RPS21, 40 S ribosomal protein S21." (PMID 30931934, 2019). "Identified were five fasting-responsive proteins that overlapped between the lines, including adaptor related protein complex 1 beta 1 subunit (AP1B1), CAPZA2, chaperonin containing TCP1 subunit 5 (CCT5), glioblastoma amplified sequence (GBAS), and 40 S ribosomal protein S21 (RPS21)." (PMID 30931934, 2019).
hepatocellular carcinoma (1 paper, 2022). A malignant tumor that arises from hepatocytes. "RPS21 and MYL6B in RI were associated with poor prognosis of patients with ESCA; they have been validated as oncoproteins in prostate tumor and hepatocellular carcinoma, respectively." (PMID 36466711, 2022).
Infertility (1 paper, 2021). "Compared with Cables2d model, the heterozygote Rps21d showed more severe phenotype including small body size, infertility, and postnatal lethality or prenatal lethality in the case of Rps21-indel." (PMID 33949947, 2021).
malignant lymphoma (1 paper, 2021). "RPS21, MRPS28, RPL31, and RPL30 showed relatively higher protein expressions in some DLBCL and other malignant lymphoma tissues than the averaged expressions in normal tissues, though not significant." (PMID 34760386, 2021).
Sepsis (1 paper, 2021). Sepsis is defined as life-threatening organ dysfunction caused by a dysregulated host response to infection. "In particular, the qPCR analysis showed significant down-regulation of RPL11, RPS21, NCBP2, and MRRF during sepsis." (PMID 34594344, 2021). "The transcription levels of RPL11 (ribosomal protein L11), RPS21 (ribosomal protein S21), NCBP2 (nuclear cap binding protein subunit 2), and MRRF (mitochondrial ribosome recycling factor) were found to be significantly reduced in the sepsis group as compared to the control group (p‐value < 0.05)." (PMID 34594344, 2021).
type 1 diabetes mellitus (1 paper, 2026). A chronic condition characterized by minimal or absent production of insulin by the pancreas. "This study reports, for the first time, the downregulation of RPS21 in DR, a finding consistent with the significantly reduced levels of RPS21 protein observed in peripheral blood samples from patients with type 1 diabetes mellitus (T1DM)." (PMID 41601931, 2026).
ulcerative colitis (1 paper, 2023). An inflammatory bowel disease involving the mucosal surface of the large intestine and rectum. "Furthermore, we observed that the upregulation of MYH11 inhibited tumor growth in GC45, and genes encoding ribosomal proteins (RPL16, RPS11, and RPS21) were related to ulcerative colitis and GC." (PMID 37488424, 2023).
tumor (9 papers, 2016 to 2024). "Interestingly, downregulation of RpS21 was previously shown to cause excessive hyperplasia in hematopoietic organs and imaginal disc overgrowth during larval development, suggesting RpS21 acts as tumor suppressor in Drosophila." (PMID 33296356, 2020). "As Ras/MAPK signaling is known to drive tissue growth in diverse settings, this may suggest that RpS21 can function as a negative regulator of tissue or tumor growth." (PMID 33296356, 2020). "Thus, RpS21 joins the ranks of an emerging number of ribosomal proteins with roles in growth suppression, although whether RpS21 acts as a tumor suppressor in mammals awaits investigation." (PMID 33296356, 2020). "Both RPS21 and HSPH1 have been reported to be involved in tumor progression." (PMID 39872660, 2024). "The other ribosomal protein gene transcripts identified in mouse mammary gland to correlate with ZFAS1, i.e. RPS21, RPS24, RPL22 and RPL28, showed significant expression differences between normal and tumour samples (*P < 0.05, **P < 0.01, ***P < 0.001, ****P < 0.0001)." (PMID 27871336, 2016).
cancer (4 papers, 2011 to 2021). A tumor composed of atypical neoplastic, often pleomorphic cells that invade other tissues. "The 20q13.33 region overlapped with several cancer related genes such as CDH4, LAMA5, RPS21, KIAA1510, TNFRSF6B (M68, DcR3), RTEL, EEF1A2 and PTK6." (PMID 24165089, 2013).
infection (4 papers, 2021 to 2025). The state of being infected such as from the introduction of a foreign agent such as serum, vaccine, antigenic substance or organism. "Previous studies comparing untreated HIV-infected individuals to healthy controls reported decreased expression of several ribosomal proteins, such as RPS27, RPL18A, RPL8, RPL26, RPL4, and RPS21, possibly reflecting impaired translational activity during active infection." (PMID 41226717, 2025). "Interestingly, transcription of genes relating to mitochondrial functions (e.g., IFI27L2a, RPS21, CARS2) were markedly upregulated only during the per-acute phase of infection (1–3 dpi), but not in 4–6 dpi." (PMID 40758745, 2025).
infectious disease (1 paper, 2022). A disorder directly resulting from the presence and activity of a microbial, viral, or parasitic agent in humans. "In the case of the pre-diagnostic markers for CD4+ T cells, the upregulated genes included ribosomal proteins (e.g. RPL39, RPL37, RPS28 and RPS21) that showed enrichments in pathways related to translation and “Infectious disease”." (PMID 35371081, 2022).
metabolic disorders (1 paper, 2026). "During DR progression, abnormal RPS21 expression may disturb the balance between ribosome and mitochondrial autophagy, resulting in metabolic disorders and retinal cell damage." (PMID 41601931, 2026).
RPS21 also shares sentences with these, for which no sentence is quoted: Deep Venous Thrombosis (1 paper); invasive breast carcinoma (1); multiple sclerosis (1); nasopharyngeal carcinoma (1); non-small cell lung carcinoma (1); prion disease (1); prostate tumor (1).